DMBT1 (deleted in malignant brain tumors 1)
Diseases named in the same sentence as DMBT1 in open-access papers (continued):
Sharing a sentence is not in itself a finding about the gene and the disease.
bone cancer (1 paper, 2022). A primary or metastatic malignant neoplasm affecting the bone or articular cartilage. "LGALS9, for example is a gene that produces Galactin-9, a well-studied protein expressed on tumour cells, and DMBT1 is a tumour suppressor gene involved in bone cancer that like IGF1R has been previously identified as key velvet antler peptide." (PMID 35151275, 2022).
cervical squamous cell carcinoma (1 paper, 2022). A squamous cell carcinoma arising from the cervical epithelium. "Malignant brain tumor 1 (DMBT1) was decreased in cervical squamous cell carcinoma (CSCC), whereas its overexpression cannot only inhibit the proliferation, migration, and invasion but also induce the apoptosis of human CSCC cells, which strongly supported our results." (PMID 35847888, 2022).
chronic gastritis (1 paper, 2015). Inflammation of the stomach that is chronic in nature. "We noticed that 6 somatic variations (ATXN3, PLIN4, PDZD2, MUC4, DMBT1 and DAB1) were simultaneously observed in triple samples of chronic gastritis, primary cancer and PM cancer." (PMID 26330360, 2015).
clonorchiasis (1 paper, 2021). Infection of the biliary passages with clonorchis sinensis, also called Opisthorchis sinensis. "Therefore, we speculate that mRNA Fmo3 and Dmbt1 might contribute to lipid metabolism and liver injury in clonorchiasis." (PMID 35127549, 2021).
congenital heart defects (1 paper, 2022). "We examined DMBT1 levels in 10 patients without cardiac defects and 18 patients with persisting ductus arteriosus (PDA) and congenital heart defects (CHD)." (PMID 34989914, 2022).
conjunctival melanoma (1 paper, 2025). "DMBT1 isoforms have previously been reported in human tears and are associated with dry eye syndrome and conjunctival melanoma." (PMID 41488750, 2025).
corneal infection (1 paper, 2017). A viral or bacterial infectious process affecting the cornea. "DMBT1 purified from human saliva also inhibited twitching, as well as P. aeruginosa traversal of human corneal epithelial cells in vitro, and reduced disease pathology in a murine model of corneal infection." (PMID 28489917, 2017).
cyst (1 paper, 2021). A sac-like closed membranous structure that may be empty or contain fluid or amorphous material. "Such comparison resulted in 4 upregulated (CP, CEACAM5, DMBT1, and KRT6A) and 8 downregulated (CEL, CPA1, CPB1, ALB, SERPINA4, CA2, CLU, and AMBP) DEGs secreted in cyst fluid of high-risk IPMNs." (PMID 34790815, 2021).
diffuse astrocytoma (1 paper, 2019). A low-grade (WHO grade II) astrocytic neoplasm. "In tumors with diffuse astrocytoma histology, DMBT1 loss may be predictive of a poor outcome, although IDH status was not assessed in that study so the status of DMBT1 as an independent predictor of outcome is unclear." (PMID 30967140, 2019).
dyslipidemia (1 paper, 2022). "However, the supplement with HFLPD inhibited DEGs of CTSE and DMBT1 in mice, suggesting that the probiotic supplement reduced the hepatic inflammation and dyslipidemia via the downregulation of these DEGs." (PMID 35743193, 2022). "The DEGs of CTSE and DMBT1 were significantly increased in response to HFD-fed animals, which confirmed that HFD might induce hepatic inflammation and dyslipidemia in mice liver by increasing the mRNA CTSE and DMBT1." (PMID 35743193, 2022).
dysplasia (1 paper, 2017). A usually neoplastic transformation of the cell, associated with altered architectural tissue patterns. "Hispanic individuals with dysplasia had significantly higher levels of DMBT1 expression when compared to MAG patients (p=0.0051)." (PMID 28423364, 2017). "Our results suggest that a significant difference in the expression of DMBT1 could be used to separate MAG from dysplasia cases." (PMID 28423364, 2017). "From NAG, the expression of DMBT1 is gradually increased through the consecutive stages of gastric carcinogenesis: MAG, IM and dysplasia." (PMID 28423364, 2017). "We identified E2F3 and DMBT1 as the genes with the largest change in expression when dysplasia samples were compared to MAG (29% reduction for E2F3 and 2.5 -fold increase for DMBT1)." (PMID 28423364, 2017).
gastritis (1 paper, 2017). Inflammation of the stomach. "In our animal model, H. pylori infection of Dmbt1−/− mice resulted in significantly higher levels of gastritis, more extensive mucous metaplasia and reduced Il33 expression levels in the gastric mucosa compared to H. pylori-infected wild type mice." (PMID 28423364, 2017).
interstitial lung disease (1 paper, 2021). A diverse group of lung diseases that affect the lung parenchyma. "Moreover, prior studies in mice have reported that DMBT1-specific immune responses lead to interstitial lung disease (autoimmune syndromes), providing substantial evidence that the autoreactivity of targeting DMBT1 was pathogenic in a subset of human interstitial lung disease patients." (PMID 34422633, 2021).
leukemia (1 paper, 2020). A malignant (clonal) hematologic disorder, involving hematopoietic stem cells and characterized by the presence of primitive or atypical myeloid or lymphoid cells in the bone marrow and the blood. "DMBT1 probably is also a tumor suppressor in leukemia and is associated with standard risk and cases with gene fusions." (PMID 32607130, 2020). "Through this technique, we identified recurrent alterations in genes DMBT1, KIAA0125 and PRDM16; these alterations were verified by qPCR and confirmed the possible involvement of these genes in the development of leukemia, especially in ALL." (PMID 32607130, 2020).
liver cancer (1 paper, 2013). An epithelial or non-epithelial malignant neoplasm that arises from the liver. "Upregulation of liver cancer stem markers, Sox9, Epcam and Dmbt1 were observed in this study." (PMID 23630614, 2013).
lung adenocarcinoma (1 paper, 2016). A carcinoma that arises from the lung and is characterized by the presence of malignant glandular epithelial cells. "We found that RSPO3, ADAMTS8, DMBT1, DOCK8, STMN2, SPINK6 and TUSC3 were the co-genes of HOXA11-AS in lung adenocarcinoma whereas RSPO3, ADAMTS8, DMBT1, DOCK8, STMN2, SPINK6, TUSC3 and C8orf22 were the co-genes of HOXA11-AS in squamous cell carcinoma." (PMID 27980454, 2016). "Additionally, ADAMTS8, DMBT1 and DOCK8 were down-regulated in adenocarcinoma and STMN2 and TUSC3 were up-regulated in lung adenocarcinoma (all P < 0.01)." (PMID 27980454, 2016). "Additionally, the original data from TCGA verified that ADAMTS8, DMBT1 and DOCK8 were downregulated in both lung adenocarcinoma and squamous cell carcinoma, whereas RSPO3 expression was upregulated in lung adenocarcinoma and downregulated in lung squamous cell carcinoma." (PMID 27980454, 2016).
lymph node metastasis (1 paper, 2025). "It has been established that high expression of the DMBT1 gene correlates with lower clinical staging, reduced risk of lymph node metastasis, and smaller tumor diameter, suggesting that DMBT1 may play a role in inhibiting the progression of PTC." (PMID 40230479, 2025).
mucositis (1 paper, 2021). Mucositis is inflammation and damage of the mucous membranes lining the mouth and other parts of the gastrointestinal (GI) tract. "We tested this hypothesis in a murine model of doxorubicin-induced mucositis by comparing WT mice expressing DMBT1 (Dmbt1+/+) with DMBT1-deficient KO mice (Dmbt1−/−)." (PMID 34282203, 2021). "In conclusion, DMBT1 does not affect doxorubicin-induced mucositis in mice." (PMID 34282203, 2021).
neuroendocrine tumors (1 paper, 2023). "DMBT1 germline deletions have been found in neuroendocrine tumors hemizygous germline deletions of DMBT1 have been found in primary brain tumors." (PMID 39086683, 2023).
ovarian carcinoma (1 paper, 2024). A malignant neoplasm originating from the surface ovarian epithelium. "It's reported that DMBT1 can also suppress ovarian cancer proliferation, migration, and invasion." (PMID 38531630, 2024).
ovarian endometriosis (1 paper, 2023). A non-neoplastic disorder characterized by the growth of endometrial tissue in the ovaries. "In our previous study, we estimated that approximately 60% of ovarian endometriosis may be originated from the tubal epithelia based on the FMO3 and DMBT1 expression study." (PMID 36936232, 2023).
pancreatic cancer (1 paper, 2021). "Though deleted in malignant brain tumour 1 (DMBT1) functions as tumour suppressor in many cancers, its huge upregulation in pancreatic cancer is also well established." (PMID 34790815, 2021).
primary sclerosing cholangitis (1 paper, 2024). "Interestingly, overexpression of DMBT1 was shown in primary sclerosing cholangitis as well as in hepatolithiasis, two common risk factors for the occurrence of LD-iCCA." (PMID 39034327, 2024).
pterygium (1 paper, 2021). A wedge-shaped fibrovascular lesion arising from the bulbar conjunctiva and extending to the cornea. "Among the top DEGs were four genes encoding tumor suppressors that were downregulated in pterygium: C10orf90, RARRES1, DMBT1 and SCGB3A1; C10orf90 and RARRES1 were also downregulated in pinguecula." (PMID 34769520, 2021). "RARRES1 and SCGB3A1 were identified in previous pterygium gene profiling studies, while C10orf90 and DMBT1 are new." (PMID 34769520, 2021).
pyelonephritis (1 paper, 2024). An inflammatory process affecting the kidney. "Alone, LL-37 and DMBT1 peptides induced membrane damage and agglutination after 3 h of co-incubation with pyelonephritis strain; CFT073." (PMID 38580392, 2024).
pyometra (1 paper, 2020). "Of those, only one protein named DMBT-1 (deleted in malignant brain tumors 1) was down-regulated, whereas 15 were up-regulated in canine pyometra." (PMID 32596263, 2020).
squamous cell carcinoma (1 paper, 2016). A carcinoma arising from squamous epithelial cells. "The original data from TCGA verified that ADAMTS8, DMBT1 and DOCK8 were down-regulated in adenocarcinoma and squamous cell carcinoma, whereas RSPO3 was overexpressed in adenocarcinoma and down-regulated in squamous cell carcinoma." (PMID 27980454, 2016). "We found that RSPO3, ADAMTS8, DMBT1 and DOCK8 were all downregulated in squamous cell carcinoma tissues compared to non-cancerous lung tissues, whereas STMN2, TUSC3 and C8orf22 were upregulated in squamous cell carcinoma (all P < 0.001)." (PMID 27980454, 2016).
thyroid (1 paper, 2019). "Chd9 and Dmbt1, among the others, are part of several complexes/gene networks regulating cell cycle/apoptosis in the endoderm and might be involved in thyroid carcinogenesis, a role not proposed until now." (PMID 30621213, 2019).
tumor (63 papers, 1999 to 2025). "Concurrently, increased expression of the DMBT1 gene, which is associated with immune defense, cell polarization, differentiation, and regeneration, exerts potential anti-tumor effects." (PMID 40230479, 2025). "Note repressed expression of RASGRF1 and DMBT1 was associated with increased tumor size, and high expression of FOSL1, FAM83A and MYEOV was associated with poor survival." (PMID 38245882, 2024). "High-drooling breeds showed higher expression of genes related to salivary secretion, particularly DMBT1, which is upregulated in Newfoundlands and linked to immune response, epithelial cell differentiation, and tumor suppression." (PMID 39580055, 2024). "Against this background, one would rather suspect DMBT1 downregulation in LD-iCCA as this subtype is commonly associated with impaired survival and a more aggressive tumor biology." (PMID 39034327, 2024). "Our results demonstrated that the high expression of DMBT1 was linked with the activation of pathways regulating immune process and tumor progression in GO analysis." (PMID 34422633, 2021). "CHAT revealed that DMBT1 is mainly correlated with genome instability and mutation, tumor-promoting inflammation, immune destruction, and evading growth suppressors." (PMID 34605357, 2021). "DMBT1 is a multifunctional protein associated with mucosal immunity and epithelial integrity, is significantly altered in GC saliva samples, and has been linked to tumor-related immune responses." (PMID 41244835, 2025). "The CRC-specific EV marker DMBT1 may act as a tumor suppressor, whose loss could be a poor prognostic factor." (PMID 32916986, 2020). "However, expression of DMBT1 in tumor cells has little effect on tumor cell growth or tumor associated phenotypes." (PMID 19653894, 2009). "Moreover, the studies demonstrated that the high-expression groups of DMBT1 might decrease the risk of tumor recurrence in PTC patients." (PMID 34422633, 2021). "Overall, H. pylori appears to promote GC progression by suppressing DMBT1, linking infection and inflammation to tumor development." (PMID 41244835, 2025). "Liver-tropic tumor cells induce CD62L-expressing KCs by a secretory protein DMBT1, and CD62L+ KCs activate neutrophils for NETosis via the chemokine CCL8." (PMID 40796724, 2025). "DMBT1 is eliminated or diminished in a number of tumor types, according to preliminary investigations." (PMID 41244835, 2025). "We also observed that treating KCs with DMBT1-overexpressing tumor CM enhanced MUC1-C nuclear localization and NF-κB activation, while the CM of cancer cells with DMBT1 knockdown had the opposite effects." (PMID 40796724, 2025). "Decreased levels of DMBT1 promote the formation of tumor cells, whereas when it is translocated to the ECM, it initiates cellular differentiation." (PMID 41244835, 2025). "Some of the genes, such as THBS1, CXCL14, and DMBT1, were notably enriched in AS_EP_STAS, suggesting their crucial role in the process of tumor cell spread into air spaces." (PMID 40786043, 2025). "Studies suggest that the DMBT1 gene has potential tumor-suppressing functions, with its expression closely associated with immune defense, cellular polarization, differentiation, and regeneration." (PMID 40230479, 2025). "In vitro studies found upregulated cellular DMBT1(deleted in malignant brain tumor 1, proposed to be a tumor suppressor gene) expression in HAECs after S. mutans infection." (PMID 39749137, 2024). "These genes include three tumour suppressors (DMBT1, MTUS1, and KLRC1), two genes involved with cell communication and myelin (GJB1 and KLK6), and a P450 monooxygenase involved in the synthesis of cholesterol and lipids (CYP4F12)." (PMID 37628980, 2023). "DMBT1 showed the most significant copy number decrease of any gene that had copy number decreases in all three EMC tumor samples in our data (copy ratio = 1.33E-09, 1.29E-09, and 4.14E-07 in primary tumor, lung metastasis, and pelvic metastasis respectively)." (PMID 39086683, 2023).
tumor (continued). "At the gene level, DMBT1 was found to have copy number decreases in all three tumor samples (copy ratio = 1.33E-09, 1.29E-09, and 4.14E-07 in P, LM, and PM respectively), as well as in PBMC." (PMID 39086683, 2023). "In our analysis, we observed an upregulation of DMBT1 (Log2FC = 4), a tumor suppressor gene known to inhibit cell proliferation and survival in various cancers." (PMID 37762335, 2023). "Since the Dmbt1 gene is deleted in several types of epithelial cancers, it is considered a tumor suppressor." (PMID 35696363, 2022). "The experimental results confirmed that ADH4 and AHNAK2 were significantly upregulated, while MMAA and DMBT1 were downregulated analogously in tumor tissues or recurrent tissues compared with controls." (PMID 35847888, 2022). "DMBT1 is a potential tumor suppressor that is located on 10q26.13 and that is characterized by intrasolar homozygous deletions and rare mutations." (PMID 34563186, 2021). "Correspondingly, the tumor purity of the high expression of DMBT1 was lower than that of the low expression of DMBT1, suggesting that more stromal cells and immune cells were infiltrated in the TME." (PMID 34422633, 2021). "The human HTRA1 gene is located on chromosome 10q25.3-q26.2, which is very close to DMBT1, suggesting HtrA1 as a presumed tumor suppressor." (PMID 34563186, 2021). "Immunohistochemistry assays demonstrated that siReg3A suppressed DMBT1 protein expression in tumor tissues." (PMID 34605357, 2021). "Extensive studies revealed that DMBT1 acts as a tumor suppressor in various types of cancer, such as lung cancer, breast cancer, digestive tract cancer, prostate cancer, gallbladder carcinoma, oral squamous cell carcinoma, and ovarian cancer)." (PMID 34605357, 2021). "Many studies have showed that DMBT1 deletion or inactivation lead to tumorigenesis by regulating infiltration and metastasis of tumor cells." (PMID 32607130, 2020). "The tumor-bearing mice that were treated with the combination of both SAM+anti-PD-1 had the significantly highest expression of Dmbt1 compared to control, SAM alone, and anti-PD-1 alone." (PMID 32983966, 2020). "DMBT1 is a tumor suppressor and involved in immune defense and epithelial differentiation in cancer." (PMID 31379917, 2019). "DMBT1 levels are elevated in biliary intraepithelial neoplasia and its absence in biliary tract of cancer patients correlates with poorer survival, thus suggesting suppressive effect DMBT1 expression on tumor growth." (PMID 29464034, 2018). "The highest over-expressed gene is DMBT1, a GC tumor suppressor and immunohistochemical marker of IM." (PMID 28441455, 2017). "The correlation analysis of DMBT1 expression revealed a significant association between DMBT1 expression and GBC tumor size (P < 0.01), tumor stage (T stage) (P < 0.01), node stage (N stage) (P < 0.01), and increased death (P < 0.01)." (PMID 27637083, 2016). "DMBT1 is a gene that is located at chromosome 10q 25.3–26.1, a possible tumor suppressor locus indicated by refinement of the losses of heterozygosity in various cancers." (PMID 26911362, 2016). "Several studies showed DMBT1 have a function of tumor-suppressor based on homologous deletions and low expression in various kinds of cancers with function in immunity, inflammation and epithelial cell differentiation." (PMID 27637083, 2016). "Dietary modulation of these genes in addition to a lower expression of other innate immune genes, including toll-like receptor 4 (Tlr4) and Dmbt1, further suggest bean feeding inhibits tumor promotion by limiting microbially induced inflammation." (PMID 22496968, 2012). "DMBT1 is proposed to be a tumor suppressor and/or a regulator of epithelial differentiation, as well as having roles in innate immune defense and inflammation." (PMID 20573196, 2010).